MUC16 (mucin 16, cell surface associated)
Diseases named in the same sentence as MUC16 in open-access papers (continued):
Sharing a sentence is not in itself a finding about the gene and the disease.
bladder cancer (16 papers, 2017 to 2025). "Nevertheless, with the exception of MUC16, the specific glycosylation patterns of this class of glycoproteins also remains unknown in bladder cancer." (PMID 29207682, 2017). "In addition, MUC16 STn+ glycoforms, characteristic of ovarian cancers, were recently described for the first time in bladder cancer and demonstrated to be expressed in a subset of advanced-stage bladder tumours facing worst prognosis." (PMID 29207682, 2017). "Among these glycoproteins were MUC16 and CD44, which have already been extensively studied in the context of bladder cancer as part of more aggressive molecular phenotypes." (PMID 34108014, 2021). "Namely, MUC16 scored 10/15 (not highlighted in the Target Score graph) and, more strikingly, CD44 (not highlighted in the Target Score graph), one of the most studied glycoproteins in bladder cancer, frequently suggested as a biomarker of cancer stem cells, scored 5/15." (PMID 34108014, 2021).
lymph node metastasis (14 papers, 2014 to 2025). "The MUC16 mutation status is associated with the TMB, MSI, survival and lymph node metastasis in GC patients." (PMID 40594780, 2025). "WFDC2 has also been demonstrated to be a more sensible predictor of lymph node metastasis (sensitivity of 0.82) in relation to MUC16 (0.72) and better in predicting myometrial invasion (AUC of 0.76) than MUC16 (AUC = 0.65)." (PMID 32560580, 2020). "tested samples of MPLC with lymph node metastasis (LNM) and found that the genes with the highest mutation frequencies in this pair were MUC16, FLNA, MUC4, FAT3, SETD2, and CALR, which implied that MPLC with LNM may have a unique mutation spectrum." (PMID 39411141, 2024). "The high-confidence driver genes RHPN2, MUC16, and MUC4 were significantly mutated in both small- and large-sized rNEN specimens, whereas mutations in MAN2A1, and BAG2 were only identified in large-sized specimens diagnosed with lymph node metastases." (PMID 39548061, 2024). "In subsequent multivariate analysis with curability as the covariate, lymph node metastasis, venous invasion, and MUC5AC and/or MUC16 expression were significantly related to the prognosis." (PMID 24722639, 2014).
liver cancer (12 papers, 2021 to 2024). An epithelial or non-epithelial malignant neoplasm that arises from the liver. "Box plots show sensitivity to regorafenib for 27 CCLE liver cancer cell lines, according to MUC16 mutational status." (PMID 36199046, 2022). "The MUC16 gene ranked 5th among the most frequently mutated genes in liver cancer." (PMID 34150633, 2021). "We speculate that these mutations may influence the structural stability of MUC16, which makes it easier for the protein to be shed from the surface of liver cancer cells and enter the serum." (PMID 34150633, 2021). "The invasion ability of tumors was enhanced when surface MUC16 was reduced in the tissues or cells of liver cancer." (PMID 34150633, 2021).
dry eye (10 papers, 2008 to 2024). "In dry eye patients, the level of membrane-associated mucins, MUC16, in conjunctival epithelial cells is altered." (PMID 26048396, 2015). "Specifically, we sought to characterize the expression of MUC16 in Sjogren’s syndrome dry eye as compared with aqueous deficient (KCS) dry eye and non dry-eyed (NDE) controls, to gain further insight into the role that MUC16 may play in dry eye disease." (PMID 19122828, 2008). "They increased the expression of inflammatory genes (e.g., IL-6) and reduced mucin production genes (e.g., MUC16), reflecting dry eye characteristics." (PMID 38379013, 2024). "In this study, we investigated the utility of the ocular surface test, which clinically evaluates mucin-related gene (SPDEF, MUC5AC, and MUC16) expression levels on the ocular surface in patients with dry eye." (PMID 33232357, 2020). "In this study, we explored the relationship between the quantity of MUC1 and MUC16 protein and mRNA with dry eye symptoms and tear stability in a cohort of PMW that were recruited without bias of specific inclusion criteria." (PMID 23687433, 2013). "The only significant difference between the two subgroups was a significant reduction in MUC16 mRNA expression found in the symptomatic dry eye group (1.52±1.19 versus 0.57±0.44; p=0.03)." (PMID 23687433, 2013). "Therefore, ocular surface mucin in this experiment was assessed with SPDEF and MUC16 mRNA expression levels and dry eye." (PMID 34194821, 2021). "A broad exploration of mucin expression compared to either a sign (NITBUT) or symptoms of dry eye failed to reveal compelling evidence supporting a significant relationship, other than a potential association between MUC16 with specific symptoms." (PMID 23687433, 2013). "We evaluated the dry eye-related quality-of-life score (DEQS), tear film breakup time (TBUT), fluorescein staining score, mRNA expression of MUC5AC and MUC16, MUC16 immunohistochemistry, and MUC5AC periodic acid Schiff (PAS) staining." (PMID 31614909, 2019). "In this study, PMW with a history of dry eye displayed significantly increased membrane-bound MUC1 and MUC16 protein and MUC1 mRNA levels compared to asymptomatic controls, prompting the hypothesis that increased mucin concentration may be a compensatory response to irritation." (PMID 23687433, 2013). "Furthermore, we have previously reported two dry eye cases for which MUC5AC and MUC16 mRNA expression on the ocular surface was increased by the concomitant use of rebamipide and steroid ophthalmic suspensions, although the increase in MUC16 mRNA levels was lower than that of MUC5AC mRNA levels." (PMID 33232357, 2020). "Thus, in the absence of symptomatic dry eye postvitreo-retinal surgery, conjunctival changes in the form of reduced goblet cell density, altered MUC4, MUC16, AQP5 and cytokines are suggestive of dry eye at a molecular level and based on goblet cell density." (PMID 32437405, 2020).
epithelial ovarian tumors (10 papers, 2006 to 2025). "Both MUC16 and mesothelin (MSLN) are highly expressed in epithelial ovarian tumors, and both soluble and cell surface-associated forms of native MUC16 interact with MSLN." (PMID 38758220, 2024). "The circulating CA125 tumor marker is an antigenic determinant encoded by the MUC16 gene, which is expressed by epithelial ovarian tumors and various other pathological forms." (PMID 32042390, 2020). "CA-125, also known as tumor antigen 125, is a high molecular weight glycoprotein produced by the MUC16 gene that is expressed on the surface of epithelial ovarian tumors and mesothelium-derived cells." (PMID 32685054, 2020). "Immunohistochemical analysis of epithelial ovarian tumors in the present study confirmed an apparent over-expression MUC16 in all induced tumors." (PMID 30287783, 2018). "Soluble MUC16 is shed into the spent harvest media of the human epithelial ovarian tumor cell line, OVCAR-3." (PMID 19538730, 2009). "In conclusion, we have provided new data on the interaction between two glycoproteins, mesothelin and MUC16, whose expression is highly upregulated by epithelial ovarian tumors." (PMID 17067392, 2006). "MUC16 is a cell surface mucin expressed at high levels by epithelial ovarian tumors." (PMID 20497550, 2010).
gynecological cancers (9 papers, 2019 to 2025). "This is supported by the fact that some of the genes and pathways identified in our analysis are associated with biomarkers currently used in the clinic, as is the case with MUC16 for gynecological cancers or CA19-9 (sialyl LewisA, a fucosylated antigen) for gastro-intestinal cancers." (PMID 38384845, 2024). "Furthermore, TTN, MUC16, CSDM3, RYR2, USH2A, and SYNE1 were frequently mutated in gynecological cancers but not in the MSK-IMPACT samples, suggesting that they play specific roles in the development of gynecological malignancies." (PMID 32626534, 2020).
COVID-19 (8 papers, 2021 to 2025). A disease caused by infection with severe acute respiratory syndrome coronavirus 2. "MUC1, MUC2, MUC4, MUC16, and MUC20 mRNA expression strongly correlated with COVID-19 severity, of which MUC1 and MUC20 mRNA expression also associated significantly with age and MUC16 and MUC20 mRNA expression with sex." (PMID 34448730, 2021). "By using the same approach, we also showed that age and mRNA expression of MUC1, MUC2, MUC4, MUC6, MUC13, MUC16, and MUC20 were the most accurate variables associated with the presence of COVID-19 among symptomatic patients (AUCROC = 91.8%; sensitivity: 90.6%; specificity: 93.3%)." (PMID 34448730, 2021). "A strong positive correlation was also seen between MUC1 and MUC2 mRNA expression and between MUC16 and MUC20 mRNA expression and specifically in the mild COVID-19 patient group." (PMID 34448730, 2021).
heart failure (8 papers, 2020 to 2025). Inability of the heart to pump blood at an adequate rate to meet tissue metabolic requirements. "It is important to note that DisGeNET has associated MUC16 with heart failure, suggesting greater relevance in the context of this study." (PMID 38473795, 2024). "In the gene MUC16, mucin 16, an association between increased MUC16 expression and heart failure (HF) has been observed in previous studies." (PMID 38473795, 2024). "Several of our patients had several pressures and fluid requirements often accompanied by heart failure, leading to congestive heart failure that was potentially responsible for MUC-16 elevation." (PMID 34608231, 2021).
squamous cell carcinoma (8 papers, 2013 to 2025). A carcinoma arising from squamous epithelial cells. "Concretely, Epi2_MUC5B represented adenocarcinoma cell (MUC5B, MUC16, MUC5AC), while Epi4_MYC harbored conventional squamous cell carcinoma features, such as high expression of KRT6A and MYC." (PMID 40657372, 2025).
glioblastoma (7 papers, 2019 to 2025). The most malignant astrocytic tumor (WHO grade IV). "After comparing common genetic alterations at baseline and after treatment in 42 patients with glioblastoma, we found that only MUC16 gene mutation frequency increased, while the remaining genes decreased." (PMID 40022576, 2025). "The study included 397 cases of glioblastoma and 61 of these cases (15.37%) showed MUC16 mutations." (PMID 35109850, 2022).
metastatic disease (7 papers, 2011 to 2024). "In particular, MUC16 levels have a strong association with metastatic disease, whereas MUC5AC has great efficacy in differentiating resectable early-stage PC from healthy controls, with significant sensitivity for disease detection when combined with CA 19-9 and almost 100% specificity." (PMID 39767746, 2024). "In our previous study, we showed de novo expression of MUC16 in the high-grade preneoplastic lesion, primary as well as metastatic PC with metastatic tumors having stronger MUC16 expression compared to the primary tumors from the same patient." (PMID 25691062, 2015). "Serum levels of MUC16/CA125 have been shown to be the strongest predictor of metastatic disease (AUC of 0.892 at 95% CI 0.846–0.938, p < 0.001) and survival (HR: 1.804, 95% CI 1.22–2.66, p = 0.003) compared to other markers (including CEA) in 180 PDAC patients." (PMID 36670203, 2023). "Patients with GC who have the MUC16 wild type may need more complete examinations to discover early metastatic tumor specimens." (PMID 36051359, 2022). "A strong expression pattern of MUC16 was observed in matched primary tumors and metastatic tumors at all the sites examined (liver, lung, lymph nodes and omentum/diaphragm) suggesting that MUC16 could be playing an important role in the progression and metastasis of PC." (PMID 22066010, 2011). "MUC16 was not expressed in any of the non-neoplastic ducts, while the primary and metastatic tumors from the same patient expressed MUC16 with nearly the same intensity." (PMID 22066010, 2011).
pancreatic adenocarcinoma (7 papers, 2011 to 2024). "Transmembrane mucins, MUC4 and MUC16 are associated with tumor progression and metastatic potential in human pancreatic adenocarcinoma." (PMID 24204560, 2013). "For example, knockout of C1GALT1 led to the truncation of O-glycosylation on MUC16 in pancreatic adenocarcinoma." (PMID 34452648, 2021). "In conclusion, our study shows that MUC16 is expressed only in pancreatic adenocarcinomas when compared to undetectable levels in the normal pancreas." (PMID 22066010, 2011). "MUC16, a transmembrane mucin, facilitates pancreatic adenocarcinoma progression and metastasis." (PMID 26046375, 2015).
cholangiocarcinoma (6 papers, 2014 to 2025). A carcinoma that arises from the intrahepatic biliary tree (intrahepatic cholangiocarcinoma) or from the junction, or adjacent to the junction, of the right and left hepatic ducts (hilar cholangiocarcinoma). "Researchers have found that MUC16(+) is an independent risk factor for poor survival in some cancer patients, and the OS of patients with MUC16(+) cholangiocarcinoma (27.4 months) is significantly lower than that of patients with MUC16(-) (56.1 months)." (PMID 40655139, 2025). "MUC16 expression is a poor prognostic factor in cholangiocarcinoma and small intestinal cancer, and was related to positive lymph node metastasis, positive venous invasion and non-curative resection in appendiceal carcinoma in the current study." (PMID 25551773, 2014). "The data on MUC16 expression in cholangiocarcinoma (CCA) tissue are very limited." (PMID 36230626, 2022).
gastric adenocarcinoma (6 papers, 2018 to 2023). "MUC16 mutations were found to be associated with higher tumor mutation load, better survival outcomes, and immune response and cell cycle pathways in gastric adenocarcinoma." (PMID 34540650, 2021). "Combining Kaplan–Meier survival analysis log-rank p-value, mutation coexistence pattern, and the result of random survival forest algorithm, we selected UTRN, MUC16, CCDC178, and HYDIN as candidates for an accurate prediction of survival in gastric adenocarcinoma patients." (PMID 34540650, 2021).
mesothelioma (6 papers, 2009 to 2025). A usually malignant and aggressive neoplasm of the mesothelium which is often associated with exposure to asbestos. "In particular lung, ovarian, pancreatic, colorectal and mesothelioma cancers have been reported to express the immunosuppressive MUC16/CA125 HIO factor." (PMID 37195923, 2023). "MUC16 has been previously demonstrated to be important in the metastasis of solid tumors to the central nervous system via its interaction with mesothelin, a protein differentially expressed in normal mesothelial cells, mesotheliomas and some other mesenchymal malignancies." (PMID 22066010, 2011). "Additionally, the blockage of MSLN with MUC16 by anti-MSLN antibodies can inhibit cancer cell expansion and metastasis and exert therapeutic efficacy in mesotheliomas." (PMID 40266223, 2025).
non-small cell lung carcinoma (6 papers, 2019 to 2024). A group of at least three distinct histological types of lung cancer, including non-small cell squamous cell carcinoma, adenocarcinoma, and large cell carcinoma. "In non-small cell lung cancer, high expression of MUC16 is associated with family history of familial lung cancer (FLC) and indoor air pollution." (PMID 38758220, 2024). "Aberrantly expressed onco-mucin 16 (MUC16) and its post-cleavage generated surface tethered carboxy-terminal (MUC16-Cter) domain are strongly associated with poor prognosis and lethality of pancreatic (PC) and non-small cell lung cancer (NSCLC)." (PMID 37567918, 2023).
Sjogren syndrome (6 papers, 2008 to 2021). An autoimmune disorder in which immune cells attack and destroy the glands that produce tears and saliva. "In previous studies, rebamipide increased MUC16 gene expression in cultured corneal epithelial cells and in a murine model of primary Sjögren’s syndrome." (PMID 33232357, 2020). "We propose that conjunctival cells in Sjogren’s syndrome increase their production of MUC16 as a compensatory mechanism to maintain their healthy phenotype." (PMID 19122828, 2008). "Sjogren syndrome patients exhibited increased soluble MUC16." (PMID 32437405, 2020). "In our investigation on ocular surface mucin alterations in Sjögren's syndrome, we reported that SPDEF and MUC16 mRNA expression levels are suitable markers for ocular surface mucin in the patients with Sjögren's syndrome." (PMID 34194821, 2021).
Pleural effusion (5 papers, 2013 to 2026). The presence of an excessive amount of fluid in the pleural cavity. "Humans CA-125, encoded by MUC16 gene, contains about 22,000 amino acids and is heavily glycosylated at the extracellular region, which can be released from the cell surface by undergoing proteolytic cleavage and hence released into body fluid, including blood, pleural effusion, and ascites." (PMID 24252645, 2013).
pneumonia (5 papers, 2012 to 2026). An acute, acute and chronic, or chronic inflammation focally or diffusely affecting the lung parenchyma, caused by an infection in one or both of the lungs (by bacteria, viruses, fungi, or mycoplasma.). "Western blot analyses indicated that only bacterial culture filtrates from strain SP168, which causes epidemic conjunctivitis, and serotype 11A, which has been associated with conjunctivitis and pneumonia, induced MUC16 ectodomain release." (PMID 22412870, 2012). "Definitive proof that ZmpC is a virulence factor for conjunctivitis and pneumonia in vivo through its sheddase activity for MUC16, awaits the development of an appropriate animal model." (PMID 22412870, 2012). "Demonstration that ZmpC is a sheddase specific for MUC16 may be most relevant to its potential virulence factor activity in pneumonia and conjunctivitis, since the tracheobronchial and ocular surface epithelia express high levels of the MAMs on their mucosal surfaces." (PMID 22412870, 2012).
thyroid cancer (5 papers, 2018 to 2025). "For instance, only two known cancer genes were found to be mutated in over 5% of thymomas (MUC16 and HRAS), testicular germ cell tumours (KRAS and KIT), and thyroid carcinomas (BRAF and NRAS)." (PMID 37550388, 2023). "The analysis showed that the gene expression level of JMJD1C, MUC16 and SLA were statistically down-regulated while the gene expression level of PDZD2 and RYR1 were up-regulated in thyroid cancer with respect to normal thyroid tissues." (PMID 35996174, 2022).